AFP (alpha fetoprotein)
Diseases named in the same sentence as AFP in open-access papers (continued):
Sharing a sentence is not in itself a finding about the gene and the disease.
tumor (continued). "In antitumor immunity, the same cell subsets recognize tumor antigens, for example, AFP and GPC3, via the T cell receptor (TCR) and exert specific cytotoxicity against HCC cells." (PMID 41375072, 2025). "Race, Sequence number, Tumor size, T stage and AFP were identified as independent predictors of LNM." (PMID 40718824, 2025). "In the multivariate analysis, we found that the baseline AFP ≥ 400 ng/ml and initial tumor shape irregularity were both significant independent factors predicting the prognosis of patients with HCC undergoing immunotherapy." (PMID 39714631, 2025). "These criteria seem to include more elements than just radiologic findings from the very first Milan criteria, including the biology of the tumor and biomarkers, such as AFP, PIVKA-II, and more." (PMID 40218170, 2025). "In the univariate analysis, multiple tumors (p = 0.03), tumor diameter >5 cm (p < 0.01), portal vein invasion (p < 0.01), alpha‐fetoprotein level >10 ng/ml (p = 0.01), and high NPS (p = 0.04) were significantly associated with poor OS." (PMID 39631788, 2025). "We chose AFP as an analyte to demonstrate the applications of our UGNA‐based sensing platform in tumor biomarker detection." (PMID 40693399, 2025). "Second-generation tumor markers (1960–1970) emerged following a pivotal discovery of AFP in mice inoculated with liver cancer cells (in 1963)." (PMID 40723883, 2025). "We observed that after 6 months, AFP levels were significantly lower in the combination group than in the monotherapy group, indicating a greater reduction in overall tumor burden with combined therapy." (PMID 41357510, 2025). "AFP, tumor diameter, and tumor number were identified as significant prognostic factors for HCC patients in this study, in agreement with recent reports." (PMID 39971810, 2025). "For tumor markers, AUC was higher at AFP ≥ 200 ng/mL (0.90 vs 0.87, P = .001) and CA19-9 ≥ 37 U/mL (0.91 vs 0.88, P = .003), indicating better diagnostic performance at elevated marker levels." (PMID 40128070, 2025). "Three months after treatment interruption, an abdominal CT scan revealed tumor progression, with AFP levels rising to 1136 μg/L." (PMID 40248448, 2025). "Despite the increase in AFP levels, subsequent scans continued to display a stable tumor size, and besides a hospitalization for chemotherapy-related neutropenic fevers, the patient reported no long-term adverse effects." (PMID 40755645, 2025). "Serum tumor markers, including CA-125, CA-19.9, alpha-fetoprotein (AFP), beta-human chorionic gonadotropin (β-hCG), and lactate dehydrogenase (LDH), were within normal limits." (PMID 41552138, 2025). "Tumor markers, including alpha-fetoprotein (AFP), carbohydrate antigen 19-9 (CA 19-9), carcinoembryonic antigen (CEA), human chorionic gonadotropin (HCG), and prostate-specific antigen (PSA), were all found to be within normal limits." (PMID 40065864, 2025). "Overall, patients who were Asian, had a higher tumor burden, or presented with AFP ≥400 ng/mL demonstrated greater OS and PFS benefits from immunotherapy." (PMID 41451207, 2025). "Immunohistochemically, the tumor cells show a focal positivity for AFP and glypican-3, CD56, S-100, GEFAP, synaptophysin, SAL4, myogenin, SSTRA2, chromogranin, NSE, and total cytokeratin." (PMID 41235104, 2025). "Empagliflozin treatment also reduced the serum levels of liver damage markers (AST, ALT, γ-GT) and AFP, a marker of tumour activity." (PMID 41471707, 2025). "Evidence has also shown that glycoprotein-based tumor markers like alpha-fetoprotein (AFP), carbohydrate antigen 19-9 (CA-19-9), or carcinoembryonic antigen (CEA) lack sensitivity and specificity." (PMID 40563578, 2025). "Gastroenterology was consulted and recommended further evaluation with tumor markers, including alpha-fetoprotein (AFP) and chromogranin A, as well as magnetic resonance imaging (MRI) of the abdomen and magnetic resonance cholangiopancreatography (MRCP)." (PMID 41181755, 2025).
tumor (continued). "Laboratory examination revealed remarkably increased serum AFP level (14248 ng/mL), whereas other serum tumor markers including CA125, CA199, CEA, and CA724 were within the normal range." (PMID 40235542, 2025). "Mazzaferro V also reported a Metroticket 2.0 model that included not only tumor size and number, but also serum AFP level." (PMID 39941874, 2025). "Variables associated with survival in the univariate analysis were donor age, recipient age, sex, alcohol etiology, Milan criteria, Retreat score, AFP levels at listing and at LT, tumor burden, microvascular invasion, tumor differentiation grade and CMVr." (PMID 40557335, 2025). "Consistent with our findings, a recent investigation revealed that CARM1 expression is notably correlated with survival and various clinical parameters, including alpha-fetoprotein levels, tumor size, satellite nodules, and microvascular invasion." (PMID 40016178, 2025). "The main prognostic factors include the stage of the disease at diagnosis, histologic type, and grade and serum tumor marker levels, such as AFP and β-HCG." (PMID 40723200, 2025). "In detail, patients were stratified based on several variables, including age, sex, HBV infection status, AFP level, tumor size, pathological grade, differentiation, resection margin, portal vein invasion, TNM stage, and SMPD3 expression level." (PMID 40226357, 2025). "Partial Dhcr7 deletion produced the most profound effect on tumorigenesis in DEN/HFD + EtOH-fed Dhcr7+/– mice, as shown by reduced tumor number, diameter, and expression of AFP and YAP, and phospho-STAT3." (PMID 40529212, 2025). "tumor size, AFP, ALT, AST, TBIL, PNI, preoperative TACE number, tumor differentiation, MVI, targeted therapy and immunotherapy, and postoperative TACE were included in the univariable Logistic regression analysis of the development set." (PMID 41463179, 2025). "Some studies suggest that baseline AFP levels before immunotherapy are related to tumor response and treatment prognosis in HCC." (PMID 39714631, 2025). "Among the 44 different clinical features, LASSO regression identified four features (fibrinogen, CEA, AFP, and tumor diameter) for constructing a predictive model." (PMID 41040508, 2025). "AFP ≥ 400 ng/ml and the initial tumor shape irregularity were both identified as significant prognostic factors for OS." (PMID 39714631, 2025). "Future research should include mechanistic studies—such as dual-luciferase assays and pathway analyses—to validate the proposed circ_0027478/miR-1236-3p/AFP axis and its regulatory impact on tumor progression via pathways like PI3K/Akt." (PMID 40429981, 2025). "Independent risk factors included increasing age (≥60 years), male sex, American Indian, Black, and White race, larger tumor size (3cm ≤ D < 5cm, 5cm ≤ D < 10cm, D ≥ 10cm), advanced T stage (T2, T3, T4), and positive AFP levels." (PMID 40718824, 2025). "The criteria include the tumor diameter, number of tumors, total tumor diameter, level of biomarkers, such as preoperative alpha-fetoprotein level, and more." (PMID 40218170, 2025). "A random-effects NMA was conducted, and subgroup analysis was performed according to the tumor number, tumor size, viral etiology, and alpha fetoprotein (AFP) level." (PMID 40703528, 2025). "Combining MER with AFP, tumor size, and BCLC resulted in improved sensitivity and specificity values of 85.7%/72.7%, 81.0%/89.5%, and 81.0%/94.4%, respectively." (PMID 40075616, 2025). "Among traditional biomarkers, alpha-fetoprotein (AFP) is a reliable predictor of tumor recurrence, yet its predictive scope remains inadequate." (PMID 41348762, 2025). "We aim to build and evaluate a model estimating the effect of alpha-fetoprotein-tumor size ratio (ATR) on the prognosis of patients undergoing hepatectomy for HCC." (PMID 40857604, 2025). "Among them, clinical markers such as AFP and tumor size, while widely used, have limitations in predicting early recurrence." (PMID 40165325, 2025).
tumor (continued). "This study found that CSC-related CTC subsets, particularly CD90(+), were more closely associated with tumor response and prognosis in unresectable HCC compared to conventional tumor markers such as AFP and DCP." (PMID 40940925, 2025). "CD90-positive circulating tumor cells perform dynamic monitoring superior to conventional markers such as alpha-fetoprotein and des-gamma-carboxy prothrombin." (PMID 40940925, 2025). "The current study investigated real-time RFS prediction by integrating time-updated AFP and tumor burden metrics." (PMID 40246743, 2025). "Regarding tumor markers associated with HCC, alpha-fetoprotein stood out in our study, showing a mean±standard deviation of 25.52±482.2 in patients without HCC and 1,941.9±9,455.6 in patients with HCC, with a statistically significant difference (P<0.001)." (PMID 41379183, 2025). "In observational analyses, this therapeutic approach is associated with more favorable outcomes in patients with a maximum tumor diameter of ≤ 3 cm, AFP, or in BCLC stage B. This approach provides a new local treatment option for HCC." (PMID 41049859, 2025). "An example of the nomogram application is as follows: A patient with the following characteristics was randomly selected: age <60 years, male, White race, a single primary tumor (one primary only), tumor size ≥10 cm, T4 stage, and AFP-positive status." (PMID 40718824, 2025). "Of the tumor markers, most were within the normal range, except for a markedly elevated serum AFP level of 6753ng/ml." (PMID 39968074, 2025). "Tumor markers were also elevated, including AFP (median [IQR], 42.1 [9.0-247.7] vs 11.3 [3.9-190.1] ng/mL) and PIVKA-II (median [IQR], 174.0 [45.7-942.7] vs 54.0 [25.0-329.0] mAU/mL) levels (both P < .001)." (PMID 40960824, 2025). "Tumor markers were markedly elevated, including α-fetoprotein (AFP) 40,948 ng/mL and protein induced by vitamin K absence or antagonist-II (PIVKA-II) 18,954 mAU/mL." (PMID 39980714, 2025). "Aside from tumor morphology, another important factor to consider would be tumor biology, and AFP has been generally used as a surrogate." (PMID 40427147, 2025). "Tumor markers showed normal levels of β-hCG and alpha-fetoprotein (AFP), but lactate dehydrogenase (LDH) was elevated at 512 U/L (normal: 140–280 U/L)." (PMID 40546337, 2025). "Univariate and multivariate analyses revealed that alpha-fetoprotein (AFP), total bilirubin (TB), postoperative ALT (ALTp), HBV infection history, tumor size, and change in AST and ALT (CAA) were independent risk factors for early recurrence (P<0.05)." (PMID 40458724, 2025). "Other factors such as age, gender, Child–Pugh score, alanine aminotransferase (ALT) level, α-fetoprotein (AFP), macrovascular tumor thrombus, extrahepatic metastasis, and CNLC stage showed limited prognostic impact for PFS or OS." (PMID 39806475, 2025). "Among 44 clinical indicators, tumor size, and AFP had the most significant predictive power, which is consistent with most prior studies." (PMID 41040508, 2025). "(2021) revealed that low STING expression in HCC patients significantly correlates with larger tumor volumes, elevated serum alpha-fetoprotein (AFP) levels, and reduced infiltration of CD8+ T cells." (PMID 41438738, 2025). "Regarding the molecular features of high-risk and low-risk groups, we observed that elevated risk scores were predominantly observed in HCC patients with age<60 years, advanced TNM stage, poor pathological grade, larger tumor size or AFP>=400 ng/ml." (PMID 41048998, 2025). "Post-operative ctDNA tumour mutational burden (TMB) positivity is associated with shorter recurrence-free survival and a higher recurrence risk compared with AFP-based monitoring." (PMID 41301037, 2025). "Recommended surveillance for three to five years includes clinical examinations every three to six months, monthly tumor markers (e.g., alpha-fetoprotein, lactate dehydrogenase), and periodic imaging of the primary site and chest." (PMID 41141134, 2025).
tumor (continued). "The model identified independent risk factors, including tumor size, CAA, history of HBV infection, TB, AFP, and postoperative ALT." (PMID 40458724, 2025). "A diagnosis of HCC was established non-invasively based on multiphasic contrast-enhanced CT demonstrating arterial-phase hyperenhancement with portal/delayed-phase washout, together with elevated tumor markers (AFP 45.9 ng/mL; PIVKA-II 121 mAU/mL)." (PMID 41450371, 2025). "In contrast, a yolk sac tumor component typically produces AFP levels far above age‐adjusted norms and warrants further evaluation." (PMID 40336679, 2025). "Tumor marker tests revealed an AFP level of 185.4 ng/ml, while squamous cell carcinoma-related antigen, cancer antigen 125 (CA125), and prostate-specific antigen (PSA) were within normal ranges." (PMID 41561743, 2025). "SynOV1.1, a lysogenic adenovirus with a synthetic genetic circuit consisting of an α-fetoprotein promoter and miRNA responsive target elements that control specific replication in alpha-fetoprotein (AFP)-positive tumor cells, has been approved by the FDA." (PMID 40114728, 2025). "AFP levels also correlate positively with key HCC indicators such as tumor size (r = 0.366, p < 0.0001), TNM (r = 0.494, p < 0.0001), and BCLC (r = 0.554, p < 0.0001)." (PMID 40429981, 2025). "These patients often have lower alpha-fetoprotein (AFP) secretion, more advanced tumor stages at diagnosis, higher levels of systemic inflammation, and a greater burden of metabolic comorbidities." (PMID 41590616, 2025). "HAS is a special subtype of GC, which is mainly characterized by the presence of hepatocyte-like differentiation regions in tumor tissues and the production of alpha-fetoprotein." (PMID 40898459, 2025). "Early alterations in CD90(+) CTC counts were observed in parallel with changes in tumor size after treatment initiation, while AFP and DCP remained largely unchanged during this period." (PMID 40940925, 2025). "Treatment with 90Y-αGPC3 significantly reduced AFP levels and the gross tumor volume, with increased apoptosis seen on histology." (PMID 40722645, 2025). "Serial measurements of serum tumor markers, including alpha-fetoprotein and beta-human chorionic gonadotropin, remained significantly decreased, indicating sustained therapeutic response." (PMID 40429559, 2025). "Serum tumor marker alpha‐fetoprotein (AFP) levels upon admission were also higher, with 86 patients (72.3%) having levels exceeding 400 ng/ml." (PMID 40823339, 2025). "Prior tumor markers such as AFP at the time of LT are known to be a potent predictor of post-transplant recurrence." (PMID 40427147, 2025). "At the same time, the results of this study demonstrated that distant metastasis, tumor diameter > 50 mm, TACE time < 2 months, and high AFP levels were independent risk factors affecting OS, which was similar to previous research results." (PMID 40678062, 2025). "The tumor marker AFP was elevated (853 ng/ml), while other markers such as CA99, CA125, CEA and PIVKA-II were unremarkable." (PMID 41293148, 2025). "The ASAR scoring system is based on albumin-bilirubin grade, tumor size, alpha-fetoprotein, and first TACE response." (PMID 39758864, 2025). "Of note, the reduced survival of patients with large tumor volume contrasts with patients who have a long waiting-list life expectancy due to their small tumor burden, such as those with low AFP and complete response to LRT." (PMID 41375030, 2025). "Several other promising CAR T-cell tumor targets were identified, including alpha-fetoprotein (AFP), Epithelial cell adhesion molecule (EpCAM), Claudin18.2 (CLD18), CD133, and c-MET61." (PMID 40626281, 2025). "Through univariate and multivariate logistic regression analysis, independent risk factors including tumor size, CAA, history of HBV infection, TB, AFP, and postoperative ALT were identified." (PMID 40458724, 2025).
tumor (continued). "The increase of AFP in the serum of these patients with cancer is the result of synthesis and secretion by cancer cells; thus, AFP is an important tumor marker for HAC." (PMID 40740864, 2025). "Tumor markers (AFP, CEA) and oxidative stress indices (MDA, 8-OHdG) were markedly decreased, while activities of hepatic antioxidants (SOD, CAT, GPx, GSH) were restored." (PMID 41228521, 2025). "Factors such as Child–Pugh Class B, bilobar tumor extent, elevated AFP (≥ 20 ng/mL), and higher platelet counts (> 150,000/μL) were identified as unfavorable predictors for CR following the initial TACE." (PMID 41025044, 2025). "AFP, vitamin K deficiency, antagonist-II induced protein (PIVKA-II) (DCP), and AFP L3 are all traditional serum tumor markers; AFP is often used as a serologic marker for the diagnosis of HCC." (PMID 40427070, 2025). "This study aims to fill this gap by comparing the levels of key tumor markers (AFP, CA 19-9, CEA, and PSA) between a sample of combustible cigarette smokers, any HTP users, and quitters." (PMID 40078230, 2025). "These radiological features, along with the tumor marker alpha-fetoprotein (AFP), were included in both univariate and multivariate analyses of the training set." (PMID 40244356, 2025). "Elevated AFP levels are not only indicative of tumor presence but are also correlated with tumor burden, progression, and prognosis." (PMID 41211432, 2025). "Postoperatively, serum tumour markers remained within normal limits: alpha-fetoprotein 1.6 ng/mL, β-hCG 0.2 mIU/mL, and LDH 139 IU/L." (PMID 41426877, 2025). "Preoperative serum tumor markers showed elevated alpha-fetoprotein (AFP, 13258 IU/mL) and beta-human chorionic gonadotropin (β-hCG, 0.3 mIU/L)." (PMID 41281142, 2025). "This study aims to explore the prognostic value of alpha-fetoprotein (AFP) and initial tumor shape irregularity in patients treated with ICIs." (PMID 39714631, 2025). "Tumor markers, including alpha fetoprotein (AFP), carcinoembryonic antigen (CEA), and Ca antigen 19-9 (CA 19-9), were within normal limits." (PMID 41531635, 2025). "After two cycles, follow-up imaging revealed evident tumor regression accompanied by a substantial decline in AFP levels, indicating a strong anti-tumor response." (PMID 41306964, 2025). "In HCC, miR-1236-3p diminishes the PI3K/Akt route by downregulating phosphatase and tensin homolog (PTEN) and AFP, thereby slowing the growth and spread of the tumor." (PMID 40429981, 2025). "Circ‐SNF2 related chromatin remodeling ATPase 5 (circ‐SMARCA5) shows abnormal expression in HCV‐related HCC tissues and is negatively correlated with tumor markers like AFP and alkaline phosphatase (ALP), indicating its potential as an early diagnostic marker." (PMID 40060195, 2025). "HCC recurrence remains a major concern after LT, with rates reported between 12–17% in large cohorts, particularly in patients beyond Milan criteria or with aggressive tumor biology (high AFP, microvascular invasion)." (PMID 41464773, 2025). "Clinical predictors of recurrence include tumour burden on the explant (excised, diseased liver), presence of vascular invasion, and elevated alpha-fetoprotein level (AFP)." (PMID 40831927, 2025). "Their ANN integrated a combination of clinical and biological features—such as tumor size, AFP level, and immune parameters like CD4 T-cell count—and outperformed conventional systems (e.g., BCLC, TNM, CLIP), achieving an AUROC of 0.866 for PFS prediction." (PMID 41008847, 2025). "Tumor markers, including alpha-fetoprotein (AFP) at 3 ng/mL (reference: <10 ng/mL) and beta-human chorionic gonadotropin (β-HCG) at <1 IU/L (reference: <5 IU/L), were also within normal ranges." (PMID 40861747, 2025). "On the other hand, the AFP tumor marker was within the normal range, with a value of 2.3 ng/mL (normal value ≤ 8.3 ng/mL)." (PMID 40959375, 2025).